SIRPA (signal regulatory protein alpha)
Diseases named in the same sentence as SIRPA in open-access papers (continued):
Sharing a sentence is not in itself a finding about the gene and the disease.
tumor (continued). "Next, we evaluated the SIRPα-αMSLN LicMAb for mediating a tumor-restricted immune response as observed by antibody-dependent cellular cytotoxicity (ADCC) and phagocytosis (ADCP)." (PMID 40402266, 2025). "The SIRPα/CD47 axis represents a crucial innate immune checkpoint that inhibits the phagocytosis of tumor cells by macrophages and monocytes." (PMID 40136470, 2025). "The CD24 and SIGLEC-10 axis is largely unchanged, however there is increased expression of CD47 on tumour cells and high levels of SIRPα on macrophages." (PMID 39788719, 2025). "Our results showed that anti-SIRPα mAb effectively inhibited the progression of the spontaneous tumor." (PMID 40523887, 2025). "Even with a 20-fold excess of RBCs or tenfold excess of lymphocytes, the SIRPα-αMSLN4D8 LicMAb was specifically bound to tumor cells." (PMID 40402266, 2025). "CD47 is a tumor-associated antigen binds to and activates signal regulatory protein α (SIRPα), an inhibitory protein expressed on the surface of macrophages, allowing tumor cells to evade innate immune surveillance." (PMID 40735642, 2025). "Anti-SIRPα antibody therapy can stimulate an influx of tumor-infiltrating NK cells and CD8+ T-cells, as well as induce DC activation and promote T-cell effector function when used in combination with anti-PD-1 antibodies." (PMID 40589735, 2025). "Previous evidence also reveals that CD47 inhibitor, namely the engineered SIRPα variant CV1 significantly in combination with IgG4 phagocytosis inducer increased the phagocytic activity of macrophages and suppressed tumor growth of xenografts in mice." (PMID 40050933, 2025). "Inhibiting the CD47/SIRPα interaction between macrophages and tumor cells has the potential to restore macrophage-driven anti-tumor immune responses mediated by TAMs." (PMID 40607438, 2025). "Blocking the CD47/SIRPα axis has been shown to enhance phagocytosis of tumor cells in vitro and promote macrophage-mediated tumor elimination in multiple in vivo tumor models." (PMID 40578556, 2025). "CD47 is a widely expressed glycoprotein that transmits a “don’t eat me” signal through interaction with signal regulatory protein α (SIRPα) on macrophages, a mechanism exploited by tumor cells to evade immune surveillance." (PMID 40963633, 2025). "CD47 is overexpressed in HCC, N-glycosylation of CD47 on N23, N34, N50, N73, N111, and N206 enhance its binding to signal-regulatory protein alpha (SIRPα) on macrophages, preventing the immune system from recognizing and eliminating tumor cells." (PMID 40040703, 2025). "CD47, a transmembrane protein, transmits a “don’t eat me” signal by binding to the macrophage surface receptor SIRPα, thereby inhibiting macrophage phagocytosis and facilitating tumor cell immune evasion." (PMID 40396172, 2025). "Our findings showed that the CD38/CD47 BsAbs strongly blocked the CD47/SIRPα interaction in CD38/CD47 double-positive tumor cells, indicating that the inhibition of CD47/SIRPα depended on the engagement of CD38." (PMID 38983860, 2024). "We began by validating the binding and functionality of soluble recombinant proteins comprising the CD47-binding ectodomain of human SiRPα (amino acids 27–371) fused to human IgG1-Fc, which has been shown to enhance tumor cell phagocytosis by macrophages." (PMID 38828721, 2024). "Inhibition of SIRPα augmented the presence of IFN-γ+ cytotoxic T cells within the tumor tissue, resulting in enhanced tumor cell eradication." (PMID 39379603, 2024). "6MW3211 efficiently disrupted PD-1/DP-L1 and CD47/SIRPα signaling and demonstrated potent therapeutic effects in three tumor models." (PMID 39588148, 2024). "Although intestinal cDC subsets are commonly classified using XCR1 and SIRPα, our analysis revealed that tumor-infiltrating cDC are rather heterogeneous with respect to the expression of these markers." (PMID 38500875, 2024). "SIRPα-expressing cells were predominantly from the myeloid lineage, and these SIRPα+ cells were abundant throughout the tumor core." (PMID 38577107, 2024).
tumor (continued). "Interaction of CD47 with SIRPA inhibits the phagocytic activity of macrophages, overcoming the expression of ‘eat me’ signals and help tumor cells to evade macrophage surveillance." (PMID 39312740, 2024). "In support, we found that in vitro ectopic lentiviral-mediated expression of mouse Id3 in mouse BMDMs resulted in their ability to phagocytose KPC tumour cells comparable to that of SIRPA blockade or of wild-type mouse KCs." (PMID 38326607, 2024). "Significantly higher levels of phosphorylated STAT3, CD206 (a TAM marker in mice) and SIRPα were present in the tumours treated with exosomes with a high ZEB1 level than in those treated with exosomes with a low ZEB1 level." (PMID 38183060, 2024). "Here, loss of detectable SIRPα signal confirmed that the blocking antibody treatment had penetrated the tumor tissue and was occupying SIRPα epitopes on myeloid cells." (PMID 38577107, 2024). "SIRPα-Fc administration resulted in increased amounts of tumor-infiltrating macrophages, enhanced TNF-α production, and a reduction in IL-10 expression." (PMID 39335665, 2024). "Target assessment via RNA sequencing and IHC confirmed the presence of SIRPα in bulk tumor samples from various solid and hematologic malignancies, and SIRPα expression correlated with the presence of macrophages." (PMID 38319147, 2024). "Another IC is the cluster of differentiation 47 (CD47), which binds to signal regulatory protein alpha (SIRPα) of membrane macrophages to inhibit tumor cell phagocytosis." (PMID 38339019, 2024). "GenSci059 selectively binds to CD47, effectively blocks the CD47/SIRPα axis signaling pathway and enhances the phagocytosis effects of macrophages toward tumor cells." (PMID 38429732, 2024). "Small molecules such as anti-SIRPA scFv (single-chain fragment variable) can also easily penetrate the tumor tissue." (PMID 38920727, 2024). "To counteract the phagocytic inhibition caused by SIRPα upregulation in CAR-M cells, we introduced a specific shRNA to silence SIRPα, which resulted in improved phagocytosis and enhanced the tumor-killing efficiency of CAR-shSIRPα macrophages." (PMID 39379603, 2024). "CD47 plays a pivotal role in cancer by delivering a "don't eat me" signal to macrophages when binding to its ligand signal-regulatory protein alpha (SIRPα) on tumor cells." (PMID 38475778, 2024). "Collectively, these findings highlighted the promising prospects of a dual blockade strategy targeting CD47/SIRPα and PD-1/PD-L1, in combination with radiotherapy, as an effective approach for achieving optimal tumor elimination." (PMID 38462636, 2024). "Blockade of the CD47/SIRPa signaling pathway enables macrophage phagocytosis of tumor cells that were otherwise protected." (PMID 38533720, 2024). "CD47, an immune checkpoint protein highly expressed on tumor cells, interacts with SIRPα on macrophages and induces phosphorylation of SIRPα to transmit a "don't eat me" signal, enabling tumor cells to evade immune surveillance." (PMID 38462636, 2024). "SPP1 + SIRPα + macrophages showed close spatial distance to tumor cells and positively correlated with PD1 + CD8 + T cells." (PMID 39696410, 2024). "CD47 acts as a defense mechanism for tumor cells by sending a “don’t eat me” signal via its bond with SIRPα." (PMID 38247566, 2024). "This engages SIRPα on the myeloid cells, skewing them toward a suppressive phenotype and inhibiting their potential to phagocytose tumor cell-derived material." (PMID 38577107, 2024). "Numerous studies of CD47/SIRPα blockades by targeting either CD47 or SIRPα have demonstrated potent anti-tumor action in preclinical models and clinical studies." (PMID 39040441, 2024). "Another key target in ICB is the CD47 which is abnormally expressed on tumor cells that bind to signal-regulatory protein alpha (SIRPα) of macrophages, and responsible for evading phagocytosis." (PMID 38169585, 2024).
tumor (continued). "Histological examination of tumor tissues through H&E staining revealed evident tumor cell death in mice treated with PD-1/SIRPα NVs, underscoring a potent therapeutic effect." (PMID 39588148, 2024). "It allows tumor cells to escape immune surveillance through its interaction with SIRPα on phagocytes, thus acting as a “don’t eat me signal”." (PMID 38720892, 2024). "Our in vitro studies demonstrate that GenSci059 effectively blocks the interaction between CD47 and its inhibitory receptor SIRPα, leading to a dose-dependent promotion of tumor cell phagocytosis by both mouse and human macrophages." (PMID 38429732, 2024). "Several antibodies have been developed to target CD47, which blocks the activation of SIRPα and reprograms TAMs to engulf tumor cells." (PMID 39516356, 2024). "Clinical significance of these findings has been translated into the development of therapeutic compounds blocking CD47 interaction with SIRPα in order to reinvigorate anti-tumor immune responses, with some of them reaching Phase I and II human trials." (PMID 39742254, 2024). "Here we have shown how SIRPα expressing myeloid cells encounter a CD47-rich microenvironment as they infiltrate the tumor." (PMID 38577107, 2024). "Tyrosine phosphorylation of SIRPα is increased in macrophages cocultured with tumour cells, resulting in SHP2 recruitment to the cell surface." (PMID 38183060, 2024). "Blockade of SIRPA rescues the expression of Dectin1/chemokines/cytokines by ID3‐ deficient KCs, thereby restoring the peritumoral anti‐tumor niche mediated by KCs, including the recruitment and activation of CD8+ T and NK cells." (PMID 39220104, 2024). "In conclusion, this study elegantly elucidates that ID3 plays a pivotal role in enhancing the anti‐tumor immune response mediated by KCs through buffering SIRPA transactivation in the liver." (PMID 39220104, 2024). "Its selective binding to pyroglutamate cycled CD47 effectively blocks the CD47/SIRPα axis signaling pathway, leading to enhanced phagocytosis of tumor cells by macrophages." (PMID 38429732, 2024). "The interaction between CD47 and signal regulatory protein alpha (SIRPα) directly hinders the phagocytosis of tumor cells by macrophages, leading to a subsequent impairment in the presentation of tumor antigens to T lymphocytes." (PMID 38532108, 2024). "Monoclonal antibodies antagonizing the interaction of CD47 with its receptor SIRPα can eliminate tumor cells in vitro and in vivo and have shown therapeutic potential in several cancers." (PMID 38773982, 2024). "CD47 + tumor cells interfere with SIRPα expressed by phagocytes from being phagocytosed and sustaining suppressed immune sensing." (PMID 39696410, 2024). "Combining radiotherapy with CD47/SIRPα blockade can further enhance the phagocytosis of macrophages, leading to a significant reduction in tumor growth." (PMID 38462636, 2024). "In a homologous mouse cancer model, SIRPα-exosomes inhibited tumor growth whilst enhancing T-cell infiltration in mice." (PMID 38281957, 2024). "The tumor weights in the control group, SIRPα-Fc group, VEGFR1-Fc group, and SIRPα-Fc + VEGFR1-Fc group were recorded as 962.36 ± 171.10 mg, 514.50 ± 83.86 mg, 381.40 ± 95.65 mg, and 68.47 ± 7.53 mg, respectively." (PMID 38532108, 2024). "The interaction between CD47 and SIRPα triggers “don’t eat me” signals from macrophages, inhibiting phagocytosis and enabling tumor cells to evade immune surveillance." (PMID 38398223, 2024). "CD47 is a ‘don’t eat me’ signal overexpressed on tumor cells and this interacts with its ligand SIRPa, which is a protein expressed on macrophages and dendritic cells, to prevent phagocytosis." (PMID 38533720, 2024). "The SIRPa-Fc-CD40L ARC fusion protein (SL-172154) is a bifunctional fusion protein that blocks CD47/SIRPa on tumour cells and CD40/CD40L on immune antigen-presenting cells." (PMID 39534871, 2024).
tumor (continued). "CD47 binds to SIRPα, a receptor in various bone marrow-derived cells, and functions as an innate inhibitory checkpoint that inhibits phagocytosis against tumor cells and the activation of downstream responses." (PMID 38612630, 2024). "As a macrophage immune checkpoint, CD47 can interact with Sirpα on macrophages to provide a “don’t eat me” signal, bind to and block Sirp-mediated phagocytosis of tumor cells." (PMID 38832992, 2024). "The ligand of CD47, SIRPα, is mainly expressed on macrophages and when their interaction occurs, its downstream signaling within tumor cells results in the dephosphorylation of multiple substrates, keeping tumor cells from phagocytosis by macrophages." (PMID 39003350, 2024). "Blocking the interaction of CD47 with its receptor, SIRPα, on macrophages enables phagocytosis and inhibits tumour progression." (PMID 38183060, 2024). "Following a treatment duration of 27 days, the tumor weights in the control group, SIRPα-Fc + VEGFR1-Fc group, and SIRPα-VEGFR1 group were measured at 905.30 ± 167.60 mg, 72.82 ± 8.65 mg, and 83.30 ± 11.71 mg, respectively." (PMID 38532108, 2024). "The suppression of tumor growth with SIRPα blockade was accompanied by a remodeling of the immune microenvironment." (PMID 38577107, 2024). "CD47 is a cell-surface ligand that is overexpressed in various malignancies and that binds to SIRPα on macrophages to promote tumor cell evasion of phagocytosis." (PMID 38464520, 2024). "In summary, the phenotype of SIRPA-positive Macro-SPP1 was similar to the macrophages engulfing tumor cells described previously." (PMID 39696410, 2024). "Based on the current paradigm, the interaction between CD47 on tumor cells and SIRPA on macrophages leads to inhibition of tumor phagocytosis." (PMID 38920727, 2024). "CD47 is a protein that is overexpressed on multiple tumor cells, inhibiting the phagocytic function of DCs by binding to SIRPα." (PMID 39334927, 2024). "It functions to inhibit macrophage phagocytosis by binding to SIRPα, aiding tumor cells in evading immune attack." (PMID 38389925, 2024). "The data collectively indicate that the concurrent utilization of angiogenetic axis blockade and CD47/SIRPα axis inhibition can effectively stimulate both the innate and adaptive immune systems, resulting in a synergistic anti-tumor response." (PMID 38532108, 2024). "Blocking the CD47/SIRPα signaling pathway can effectively promote phagocytosis of tumor cells by macrophages in vitro and in vivo." (PMID 39513610, 2024). "The cyclization of CD47 N-terminal pyroglutamate on the tumor cell surface can enhance its binding ability to SIRPα." (PMID 38429732, 2024). "CD47 is the most studied "don't eat me" signal that is overexpressed on tumor cells and inhibits macrophage activity through interaction with its receptor SIRPα." (PMID 38773982, 2024). "IGF-1 and CCL20 promote tumour progression, while SIRPα interacts with CD47 expressed on tumour cells to inhibit microglial phagocytosis." (PMID 39364322, 2024). "In the HSPCs-CDX model, we found that SIRPα-VEGFR1 elicited an effective anti-tumor effect to a similar extent as combination therapy." (PMID 39335665, 2024). "To explore the tumor-binding property of PD-1/SIRPα NVs, we added Dil-labeled nanovesicles to a dish containing the B16F10 cells and RBCs." (PMID 39588148, 2024). "Mice bearing CIN-afflicted tumors with wild-type CD47 levels succumb similar to controls, but long-term survival is maximized by SIRPα blockade on adoptively transferred myeloid cells plus anti-tumor monoclonal IgG." (PMID 38805560, 2024). "Based on tumor immune evasion, a series of immunotherapy approaches such as blocking CD47/SIRPα has been developed and clinically applied to tumor therapy." (PMID 38383737, 2024). "Using SIRPa-Fc in an immunocompetent mouse model of GBM was effective in reducing tumor size, particularly when used in combination with autophagy inhibitors." (PMID 39194679, 2024).
tumor (continued). "Monoclonal antibodies and fusion proteins blocking CD47/SIRPα signaling have demonstrated potent anti-tumor action in preclinical models and clinical studies." (PMID 39040441, 2024). "Further research is needed to better characterize the impact of SIRPα inhibition in the tumor microenvironment and the potential interactions between BMS-986351 and other therapies, including immune checkpoint inhibitors." (PMID 38319147, 2024). "In contrast, SIRPα expression was more exclusive, restricted to the myeloid, endothelial, and immune-modulatory cancer-associated fibroblast (CAF) compartments of the tumor." (PMID 38577107, 2024). "In esophageal squamous cell carcinoma, elevated SIRPα expression correlates positively with a poorer prognosis, potentially by impeding macrophage-mediated phagocytosis of tumor cells and fostering an immunosuppressive microenvironment." (PMID 38342925, 2024). "Antibodies and recombinant SIRPα constructs that block the CD47-SIRPα interaction on macrophages exhibit anti-tumor activities in mouse models and are in ongoing clinical trials for treating several human cancers." (PMID 38495618, 2024). "The upregulated CD47 in tumor cells interacts with SIRPα, which is prominently expressed on the surface of myeloid cells, triggering “don’t eat me” signals." (PMID 38398223, 2024). "Perturbation of SIRPα signaling restored phagocytosis and antigen presentation by MDSCs, which was accompanied by renewed T cell activity and delayed tumor growth in multiple solid cancers." (PMID 38577107, 2024). "Subsequently, CD47/SIRPα axis blockade was shown to effectively promote tumor cell phagocytosis as well as enhanced antigen presentation leading to a strong T cell mediated tumor response." (PMID 38322418, 2024). "The spatial analysis showed that SPP1 + SIRPα + macrophages were in closer proximity to tumor cells compared with SPP1- macrophages." (PMID 39696410, 2024). "The shorter spatial distance between SPP1 + SIRPα + macrophages and both tumor cells and CD8 + T cells enables their close crosstalk." (PMID 39696410, 2024). "Binding of CD47 to its target receptor, SIRPα, on myeloid cell lineages leads to the initiation of the downstream signaling cascades that inhibit innate immunity anti-tumor responses." (PMID 39742254, 2024). "Some studies have demonstrated that aCD47 can inhibit the interaction of CD47 and SIRPα to facilitate DC maturation and tumor cell phagocytosis by TAMs." (PMID 38560565, 2024). "Reducing complement activation removed any potential for autologous complement depletion/fixation of non-tumor cell populations, including monocytes, neutrophils, and other immune lineages expressing SIRPα." (PMID 38319147, 2024). "Intriguingly, we also detected activation of the cGAS-STING signaling pathway in CAR-Ms and SIRPα-silenced CAR-Ms upon coculture with tumor cells." (PMID 39379603, 2024). "First, the CD47/SIRPA blockade cannot effectively induce phagocytosis on its own when the cancer cells reside in the tumor mass in which TAMs exist." (PMID 38920727, 2024). "Testing SIRPα blockade in additional murine models, particularly genetically engineered tumor models, would further support our findings." (PMID 38577107, 2024). "According to the current paradigm, the interaction between CD47 on tumor cells and SIRPA on macrophages leads to the inhibition of tumor phagocytosis." (PMID 38920727, 2024). "Mice bearing palpable tumors received anti-SIRPα antibody or IgG control at days 5 and 8 post-tumor induction (when moDCs and M-MDSCs dominate the myeloid infiltrate)." (PMID 38577107, 2024). "As a result, the functional status and the phenotype of SPP1 + SIRPα + macrophages are possibly influenced by the tumor cells." (PMID 39696410, 2024). "The CD38/CD47 BsAbs had a greater ability to block the CD47/SIRPα signal in CD38+/CD47+ tumor cells than IMM01 (SIRPα Fc fusion protein)." (PMID 38983860, 2024).